XIAP (X-linked inhibitor of apoptosis)
Diseases named in the same sentence as XIAP in open-access papers (continued):
Sharing a sentence is not in itself a finding about the gene and the disease.
breast carcinoma (continued). "Next, we investigated inhibition of XIAP using a specific inhibitor; embelin and found that embelin treatment led to inhibition of cell viability and induction of apoptosis in breast cancer cells." (PMID 28893228, 2017). "We examined the expression of XIAP in more than 1000 Middle Eastern breast cancer cases by immunohistochemistry." (PMID 28893228, 2017). "Even though XIAP over-expression has been shown to have poor survival in breast cancer in other population, however, there is limited information on the role of XIAP in Middle Eastern populations." (PMID 28893228, 2017). "This is followed by in vitro and in vivo targeting of XIAP in breast cancer cells using specific XIAP inhibitor, embelin, either alone or in combination with PI3-kinase/AKT inhibitor, LY294002 to assess cell viability, apoptosis and xenograft tumor regression." (PMID 28893228, 2017). "To identify the role of XIAP in the pathogenesis of breast cancer, we analyzed expression of XIAP by IHC on a TMA format on a large cohort of BC samples collected at KFSHRC from 1990 to 2011." (PMID 28893228, 2017). "Herein, we report that ectopic expression of XIAP 3′UTR increased human breast cancer cells proliferation, colony formation, migration, invasion and xenograft tumor growth and suppressed tumor cell death." (PMID 28186968, 2017). "We found that XIAP was over-expressed in one third of our cohort of breast cancer samples and elicited a poor survival." (PMID 28893228, 2017). "Our in vitro and in vivo data clearly indicated the utility of targeting a subset of breast cancer with over-expression of XIAP and activated AKT to successfully inhibit cell growth and induce apoptosis." (PMID 28893228, 2017). "To better understand the mechanisms through which XIAP 3′UTR regulates breast cancer progression, we performed gene expression array analysis using RNA isolated from MCF-7 cells which were transfected with XIAP 3′UTR or vector stably." (PMID 28186968, 2017). "First, we demonstrated that overexpression of XIAP 3′UTR increased the proliferation rate of breast cancer cells in vitro and promoted tumor growth in vivo." (PMID 28186968, 2017). "Next, we evaluated the effect of serum starvation-induced apoptosis on XIAP expression in breast cancer cells." (PMID 28186968, 2017). "By determination of XIAP expression in common mammary epithelial and breast cancer cell lines, we selected T47D and MCF-7, as a couple of model cell lines with relatively high and low expression of XIAP respectively." (PMID 29113338, 2017). "We found that XIAP 3′UTR mRNA levels were significantly higher in breast cancer cells than in normal mammary epidermal cells." (PMID 28186968, 2017). "Reduced XIAP expression sensitizes acute myeloid leukemia cells to TRAIL-induced apoptosis, and specific downregulation of Bcl-2 and XIAP by RNAi enhances the efficacy of chemotherapeutic agents in MCF-7 human breast cancer cells." (PMID 28792527, 2017). "XIAP over-expression in our cohort of breast cancer was an independent poor prognostic marker in multivariate analysis." (PMID 28893228, 2017). "We demonstrated that increased XIAP expression significantly abrogated miR-23a mimics-promoted breast cancer cell autophagy, migration and invasion." (PMID 29113338, 2017). "In the present study, we found that XIAP 3′UTR is a tumor promoter in breast cancer cells in vitro and in vivo functional assays." (PMID 28186968, 2017). "Herceptin plus FKA treatment leads to an enhanced growth inhibitory effect on HER-2 overexpressing breast cancer cell lines through downregulation of Myt1, Wee1, Skp2, survivin, and XIAP." (PMID 28335434, 2017). "Herein, to investigate the regulatory mechanism of XIAP in cell autophagy, we scanned several miRNAs and identified miR-23a as a target miRNA for XIAP-mediated autophagy and also play a role in cell viability, invasion and migration of breast cancer." (PMID 29113338, 2017).
breast carcinoma (continued). "In contrast to in cardiomyocytes, overexpression of CCN1in human breast cancer MCF-7 cells upregulates XIAP expression to promote chemoresistance to paclitaxel, Adriamycin, and β-lapachone through integrin αvβ3/αvβ5 and NFκB signaling pathway." (PMID 27167338, 2016). "XIAP has been reported to be upregulated in many cancers, including acute and chronic leukemia, prostate cancer, breast cancer, and many other cancers." (PMID 27447744, 2016). "Similar trends were reported in colorectal and breast cancer cell lines, where ceramide was found to effectively sensitise cells to apoptosis and also suppress tumour progression, via targeting of XIAP." (PMID 26071313, 2015). "We previously showed that TRIP-Br1 acts as an anti-apoptotic protein by stabilizing the XIAP in breast cancer cells." (PMID 25691055, 2015). "In this study, we demonstrated that aromatic ceramide analog LCL85 effectively overcomes metastatic human colon and breast cancer cell resistance to Fas-mediated apoptosis at least partially through inducing proteasomal degradation of cIAP1 and xIAP in vitro." (PMID 24422988, 2014). "Our study found that natural products with proteasomal inhibitory activity suppressed NF-κB activation, resulting in inhibition of XIAP expression, leading to enhanced apoptosis in breast cancer cells." (PMID 25419573, 2014). "Here, we identified xIAP and cIAP1 as targets of the ceramide signaling pathways in both metastatic human colon and breast cancer cells." (PMID 24422988, 2014). "It has been determined previously that there is an increase in the expression of IAPs (Survivin and XIAP) in colon, lung and breast cancer." (PMID 24581231, 2014). "We observed that LCL85 effectively decreased cIAP1 and xIAP protein levels in metastatic human colon and breast cancer cells." (PMID 24422988, 2014). "TQ also inhibited the protein expression of anti-apoptotic genes, such as XIAP, survivin, Bcl-xL and Bcl-2, in breast cancer cells and breast tumor xenograft." (PMID 24098377, 2013). "Taken together, these results suggest synergistic inhibition of XIAP mediated p-Akt, which in turn regulates downstream targets in inducing breast cancer apoptosis." (PMID 23613836, 2013). "The ability of XIAP to inhibit caspases is thought to contribute chemoresistance in breast cancer and also act as adverse prognostic factor." (PMID 23613836, 2013). "In a line, our preclinical studies showed effective approach with promising results in this synergistic combination of TQ-TAM, possibly direct future clinical development of XIAP mediated p-Akt inhibition in breast cancer." (PMID 23613836, 2013). "Although it has been demonstrated that the nuclear localization of XIAP is an independent prognostic marker in breast cancer, little is known about the expression and subcellular localization relevance of XIAP in CML patient samples." (PMID 23259070, 2012). "It was important for us to demonstrate the XIAP nuclear staining is genuine, and we were going to practice it in breast cancer cell lines in following study." (PMID 21645409, 2011). "XIAP is also known to direct the activity of NF-κB as it is an essential component in TGF-β signaling that stimulates NF-κB in metastatic 4T1 breast cancer cells." (PMID 21789165, 2011). "When XIAP was targeted in these inflammatory breast cancer cell lines, a greater decrease in cell viability was observed in combination with Trastuzumab than with Trastuzumab treatment alone." (PMID 19563669, 2009). "The apoptotic response of some breast cancer cell lines to targeted therapies is therefore enhanced either by siRNA-mediated depletion of XIAP or by targeting multiple IAPs with a Smac mimetic." (PMID 19563669, 2009). "Four members of the IAP family, Survivin, XIAP, cIAP1 and cIAP2, were all expressed to varying extents in breast cancer cell lines or tumours." (PMID 19563669, 2009).
breast carcinoma (continued). "To show that XIAP antagonism augments drug-induced apoptosis in breast cancer cells, we initially examined its effects in conjunction with TRAIL." (PMID 19563669, 2009). "IAPs, in particular XIAP and cIAPs, are therefore potential targets for lowering the apoptotic threshold of breast cancers, making them more sensitive to therapeutic drugs." (PMID 19563669, 2009). "Smac-mimetic IAP-antagonists sensitize TRAIL-induced apoptosis by blocking XIAP function in multiple tumor models, including breast cancer, multiple myeloma, glioblastoma and ovarian cancer." (PMID 19895686, 2009). "We show that inhibiting IAPs either using siRNA directed against XIAP or using a Smac mimetic overcomes the intrinsic resistance of some of the breast cancer cell lines to both TRAIL and targeted therapies against ErbB receptors." (PMID 19563669, 2009). "In breast cancers that are resistant to anthracyclines or taxanes, it was noted that the X-linked inhibitor of apoptosis (XIAP) is generally upregulated and overexpressed." (PMID 40940922, 2025). "Furthermore, XIAP induces resistance to tyrosine kinase inhibitors such as Lapatinib in breast cancer, and Imatinib in acute myeloid leukemia (AML)." (PMID 40223934, 2025). "In the present study, we investigated the expression profile of the XIAP-driven ASR gene set in breast cancer subtypes, identified race-related differentially expressed genes within this gene set, and determined associations between ASR gene expression and poor survival outcomes." (PMID 35697736, 2022). "At the clinical level, 99% of XIAP expression was reported in breast cancer patients." (PMID 36358282, 2022). "In this case, we demonstrate that the new flavanone isolated from leaves of Chomolaena tacotana has a promising and selective anti-breast cancer potential that includes the induction of intrinsic apoptosis by downregulation of the anti-apoptotic proteins XIAP and Bcl-2." (PMID 36615253, 2022). "Our present study clearly shows that DMF induces apoptosis through decreased Survivin, XIAP, Bcl-xL, and Bcl-2 expression via inhibition of NF-κB activation and potentiates the apoptosis-inducing effect of adriamycin and paclitaxel in human breast cancer cells." (PMID 35955813, 2022). "Our predicted results obtained by molecular modeling suggest the binding mode of Tacotanina to the BIR3 domain of XIAP, and are consistent with the downregulation of XIAP and subsequent enhanced levels of cleaved-Caspase-3 observed in breast cancer cells treated with Tacotanina to promote apoptosis." (PMID 36615253, 2022). "The Western blot analysis demonstrates that PTXNR-TTZ activates the effector caspase proteins in HER2 positive breast cancer cells, and downregulates the anti-apoptotic XIAP facilitating caspase-dependent apoptosis followed by the cell cycle arrest in the G2/M phase." (PMID 33795712, 2021). "Another recent study has shown that X-linked inhibitor of apoptosis protein (XIAP) functioned as a ubiquitination E3 ligase toward p62 and suppressed p62 expression through ubiquitin-proteasomal degradation and therefore promoted breast cancer progression." (PMID 34164402, 2021). "XIAP was highly expressed in human breast cancer cell lines and tissue samples from patients." (PMID 33138314, 2020). "The expression of XIAP was reduced in MCF-7 breast cancer cells by siRNA." (PMID 32537125, 2020). "Previously, BS-181 was reported to induce G1-arrest and apoptosis, resulting from the down-regulation of G1 cyclin (cyclin D1) and anti-apoptotic proteins (MCL-1 and XIAP) in breast cancer cells and down-regulation of cyclin D1 and XIAP in gastric cancer cells." (PMID 33352782, 2020). "Nevertheless, very little was found on the XIAP functional mechanism in breast cancer." (PMID 32537125, 2020). "FOXM1 can also target XIAP and Survivin to modulate breast cancer survival and chemoresistance." (PMID 33371405, 2020).
breast carcinoma (continued). "Previous evidence indicates that Toll-like receptor 4 contributes to the development of paclitaxel resistance in advanced breast cancer cells by increasing the expression of pro-inflammatory cytokines such as IL-6 and IL-8, as well as the anti-apoptotic protein XIAP." (PMID 33324567, 2020). "Studies have shown that tetrac affects only XIAP gene expression in breast cancer cells." (PMID 30915033, 2019). "Moreover, in breast cancer cells, a knockdown of RPS3 induces apoptosis by downregulating X-linked inhibitor of apoptosis (XIAP)." (PMID 30213050, 2018). "Our in vitro and in vivo preclinical studies identify the cellular stress-mediated induction of the XIAP-NFκB signaling axis as a novel mechanism of immune evasion and reveal the potential of targeting this signaling pathway to improve breast cancer immunotherapy." (PMID 30400822, 2018). "The patient poor survival in our cohort worsened significantly if the tumors co-expressed both PARP and XIAP, which could suggest that these two genetic deregulations might synergistically affect the survival outcome of breast cancer in this ethnicity." (PMID 30647872, 2018). "Finally, we demonstrated that miR-23a enhanced breast cancer cell autophagic activity through modulation of XIAP expression and also promoted cell migration and invasion." (PMID 29113338, 2017). "To determine the role of XIAP 3′UTR, we forced the expression of XIAP 3′UTR in breast cancer cells." (PMID 28186968, 2017). "This phenomenon can be explained by the increased amount of anti-apoptotic proteins caused by XIAP 3′UTR, since increased XIAP 3′UTR levels could bind and arrest the function of endogenous miRNAs in breast cancer cells." (PMID 28186968, 2017). "Inspired by above theory, we hypothesized that the XIAP 3′UTR served as a ceRNA for FSCN1 in breast cancer." (PMID 28186968, 2017). "Moreover, we found that XIAP 3′UTR-transfected breast cancer cells had significantly higher levels of FSCN1 and XIAP protein and mRNA compared to control cells." (PMID 28186968, 2017). "In the present study, we demonstrated that miR-489 targeted XIAP in breast cancer." (PMID 29371950, 2017). "In this study, we have investigated expression of XIAP in a large cohort of more than 1000 clinical breast cancer samples in tissue microarray (TMA) format by immunohistochemistry and determined the association of XIAP over-expression with various clinical parameters and molecular markers." (PMID 28893228, 2017). "In addition, FKA enhanced the growth inhibitory effect of HER2 specific antibody Herceptin on HER2-overexpressing breast cancer cell line by down-regulation of Myt1, Wee1, survivin, and XIAP." (PMID 28335434, 2017). "However, further in-depth studies are required to study the efficiency and associated toxicities of these agents before they can be fully utilized for the management of sub-group of breast cancer with XIAP over-expression." (PMID 28893228, 2017). "The combined effect of Herceptin and FKA on downregulation of Cdc2 inhibitors (i.e., Myt1 and Wee1) and inhibitors of apoptosis (i.e., survivin and XIAP) is likely attributable to the enhanced growth inhibition of HER2-overexpressing breast cancer cells by these two agents." (PMID 28335434, 2017). "In addition, the protein expression of anti-apoptotic genes, such as XIAP, survivin, Bcl-xL and Bcl-2, was inhibited by thymoquinone in breast cancer cells and breast tumor xenograft." (PMID 27529277, 2016). "This study further showed that WA and Cel induce apoptosis in human breast cancer cells through inhibition of the nuclear translocation of NF-κB and downregulation of the expression of XIAP (mRNA and protein) and cIAP1/2 (mRNA), resulting in increased levels of caspase-3 and -9 proteins." (PMID 25419573, 2014). "Furthermore, increased inhibition of XIAP resulting in apoptosis was observed in these breast cancer cells when treated with a combination of TNF-α and WA or Cel." (PMID 25419573, 2014).
breast carcinoma (continued). "Moreover, marked inhibition of the levels of survivin, XIAP, and cIAP1 was also detected in the resistant breast cancer MCF-7/ADR cells." (PMID 24830744, 2014). "The current study indicates that survivin and XIAP could be directly regulated by NF-κB p65 subunit, thus functioning anti-apoptosis in breast cancer cells." (PMID 23402310, 2013). "Indeed, increased BCL2 and XIAP protein contents were found in tumour spheroids of lung and breast cancer cells, respectively, in comparison to the corresponding monolayer cell cultures." (PMID 22797576, 2012). "XIAP is a known inhibitor of apoptosis, and transmits survival signals in breast cancer cells." (PMID 22824293, 2012). "Experiments in vitro identified that down regulation of XIAP expression or applying Smac mimics could sensitize breast cancer cells to chemotherapeutics and promote apoptosis." (PMID 21645409, 2011). "Interestingly, in presence of downregulated levels of XIAP, there is an accumulation of the cleaved p43 and p41 forms of caspase-8, both in melanoma and mammary carcinoma cell lines." (PMID 20461078, 2010). "Interestingly, elevated Survivin, XIAP and cIAP1 levels were detected in cells corresponding to the early stages of breast cancer progression, in atypias (MCF10neoT and MCF10AT1 cells) and in MCF10DCIS-like cells." (PMID 19563669, 2009). "Thus, high expression of XIAP has been reported in many malignant tumour types, such as carcinomas of the breast, ovaries, lung, pancreas, cervix and prostate as well as leukaemias." (PMID 15328523, 2004). "In breast cancer cells, hyperoside has been reported to modulate intracellular ROS levels and inhibit the NF-κB pathway, leading to a decrease in the expression of anti-apoptotic genes such as XIAP and Bcl-2, while promoting the accumulation of Bax, a pro-apoptotic factor." (PMID 40942095, 2025). "Additionally, USP11 interacts with XIAP to suppress apoptosis in breast cancer cells." (PMID 38722330, 2024). "FoxM1 could target XIAP and survivin to promote cell growth and chemoresistance of breast cancer." (PMID 36860922, 2023). "However, in further research, it might be possible to determine the regulated proteins by XIAP in different breast cancer cell lines." (PMID 32537125, 2020). "The overexpression of X-linked inhibitor of apoptosis (XIAP), a potent caspase inhibitor member of the inhibitor of apoptosis proteins (IAP) family, is associated with aggressiveness and resistance to chemotherapy and targeted therapy in breast cancer and other malignancies." (PMID 32272610, 2020). "By scanning several miRNAs potentially targeting XIAP, we observed that forced expression of miR-23a significantly decreased the expression of XIAP and promoted autophagy, wherever down-regulation of miR-23a increased XIAPexpression and suppressed autophagy in breast cancer cells." (PMID 29113338, 2017). "Therefore, we cloned the XIAP 3′UTR constructs into breast cancer cells." (PMID 28186968, 2017). "Therefore, our study demonstrates that miR-23a modulates XIAP-mediated autophagy and promotes survival and migration in breast cancer cells and hence provides important new insights into the understanding of the development and progression of breast cancer." (PMID 29113338, 2017). "Importantly, this pharmacological rescue results in TGFβ signaling dependent induction of apoptosis through disruption of survivin/XIAP mediated cell survival as seen both in vitro and in vivo in the 2 cell lines studied here as well as a pancreatic cancer cell line and 3 breast cancer cell lines." (PMID 22672900, 2012). "Currently there are surprisingly few studies on XIAP in breast cancer, and these few have focused on a limited number of cell lines; to our knowledge, only one other study has examined its in vivo expression in comparison with normal breast, where XIAP positivity correlated with tumour grade." (PMID 19563669, 2009).